EGFR (epidermal growth factor receptor)
Diseases named in the same sentence as EGFR in open-access papers (continued):
Sharing a sentence is not in itself a finding about the gene and the disease.
lung cancer (continued). "Mutations in the EGFR-TK domain have been linked to gefitinib sensitivity in a subset of lung cancers, and have also been found to activate anti-apoptotic pathways." (PMID 22957020, 2012). "In EGFR mutant lung cancer cells, inhibition of PI3K/mTOR and MEK were directly linked to MCL-1 downregulation and BIM upregulation, respectively." (PMID 22808163, 2012). "In lung cancer patients, EGFR mutations are generally exclusive with KRAS and BRAF mutations, and tumors with either KRAS (15–25%) or BRAF (2-3%) mutations are relatively insensitive to EGFR TKIs." (PMID 22970367, 2012). "Like in lung cancer, the EGFR mutation profiles seem to be related to the ethnical origin of patients." (PMID 22293080, 2012). "Molecular screenings showed that the presence of an EGFR activating mutation was highly linked to tumor response and EGFR mutated tumors were defined as a new entity among lung cancers." (PMID 22272264, 2012). "The present review focuses on the roles of epidermal growth factor receptor (EGFR), microRNAs (miRNAs), autophagy and cancer stem cells in lung cancer therapy, and provides a synopsis of the association of curcumin and these recently established targets." (PMID 22489192, 2012). "Similar to EGFR mutations in lung cancer, EML4-ALK mutations occur primarily in the adenocarcinoma subtype, and usually occur in never- and light-smokers." (PMID 22928112, 2012). "Next, associations of the ‘anti-EGFR/MET’ lipid metabolism genes with other genes were evaluated by calculation of the intergene Pearson correlation coefficients in lung cancer samples." (PMID 22211244, 2012). "MET amplification activates ERBB3/PI3K/AKT signaling in EGFR-mutant lung cancers and causes resistance to EGFR TKIs." (PMID 23691449, 2012). "Despite this, up to 80% of adenocarcinoma (not limited to lung cancer) harbor EGFR mutations and it is possible that autophagy as a mechanism of acquired resistance is also present in other EGFR mutated cancers." (PMID 23119048, 2012). "Yet, clinical trials revealed activity against lung cancers having K-RAS mutations when an EGFR-TKI was combined with a rexinoid." (PMID 22923130, 2012). "Mutation of the epidermal growth factor receptor gene (exon 21, L858R) in lung cancer cells was detected, and treatment with gefitinib was initiated." (PMID 22947115, 2012). "Recently, mutations in PIK3CA were identified in ~5% of EGFR mutant lung cancers that developed acquired EGFR TKI resistance." (PMID 22970367, 2012). "Further experience and the understanding of the lung cancer molecular biology are required for the better treatment of the cases with both EGFR mutation and EML4-ALK fusion gene." (PMID 23181703, 2012). "Epidermal growth factor receptor (EGFR) has been in the focus of this lung cancer science and specific activating mutations are eligible for the treatment with specific tyrosine kinase inhibitors like gefitinib or erlotinib." (PMID 23088930, 2012). "What is more, therapy- induced disappearance of previous molecular alterations in the same tumor has also been described before, i.e. the loss of epidermal growth factor receptor gene mutation in lung cancer with natural resistance to gefitinib (IRESSA)." (PMID 22844452, 2012). "There is also clinical evidence of the association of PTEN with prolonged survival after gefitinib treatment in EGFR-mutated lung cancer patients." (PMID 23691449, 2012). "The mutation of epidermal growth factor receptor is a highlight of lung cancer diagnosis and therapy." (PMID 23031673, 2012). "Complementary, EGFR mutations were firstly reported in lung cancer patients who had greater response to treatment with EGFR tyrosine kinase inhibitors." (PMID 23207070, 2012). "Activating mutations in the EGFR catalytic domain plays an important role in determining the responsiveness to anti-EGFR therapy in lung cancer." (PMID 22043994, 2012).
lung cancer (continued). "The OS of 46 gefitinib-treated lung cancer patients, with follow-up until June 30, 2011, was studied in reference to the EGFR polymorphism status." (PMID 23226726, 2012). "Two activating EGFR mutations that confer gefitinib sensitivity to certain lung cancers were tested: EGFR[L858R] and EGFR[Δ747–752]." (PMID 22957020, 2012). "The study of EGFR mutations in patients with lung carcinomas is complicated in the real clinical world by two interconnected factors." (PMID 22952784, 2012). "To determine the EGFR polymorphism status and its correlation with clinicopathological features in lung carcinoma in the Japanese population, we investigated EGFR gene status using TaqMan single nucleotide polymorphism (SNP) genotyping assays." (PMID 23226726, 2012). "A subset of lung cancer patients harbour EGFR somatic mutations in their tumours and are candidates for treatment with EGFR tyrosine kinase inhibitors." (PMID 21575252, 2011). "We retrospectively reviewed the association of the EGFR mutation status of nonsmall cell lung cancer and pulmonary diseases." (PMID 22191026, 2011). "In lung cancer, these inhibitors are used to treat cancers that harbor exon 20 variants, codon 719 variants, and L858R substitutions in addition to other types of EGFR mutations." (PMID 21931712, 2011). "EGF receptor (EGFR) is frequently overexpressed in many types of cancers, including breast cancer and lung cancer, and is highly implicated in their malignancy." (PMID 21966491, 2011). "It is well-known that EGFR participates in the development and progression of lung cancer, and its amplifications and mutations correlate with effective response to several EGFR tyrosine kinase inhibitors (TKIs) for NSCLC therapy." (PMID 21935476, 2011). "Because variations in the frequency of EGFR-activating mutations in East Asians and other patients with lung cancer have been described, we evaluated the EGFR mutational profile in tumour samples from European patients with TNBC." (PMID 22192147, 2011). "Overexpression or mutation of EGFR has been observed in lung cancers, and these molecular changes affect the prognosis and treatment sensitivity of patients." (PMID 21333004, 2011). "Acquired resistance to cetuximab has been linked to increased levels of nuclear EGFR in lung cancer while lapatinib supposedly inhibits nuclear translocation of both EGFR and HER2." (PMID 22091418, 2011). "In lung cancers, EGFR mutations were found to predict an excellent response to EGFR TKIs but these are only found in a small number of patients." (PMID 21908901, 2011). "It is reported in some studies that EGFR gene mutations in the tyrosine kinase domain in patients with lung cancer are accompanied with a low increase in EGFR gene copy number." (PMID 22132735, 2011). "At present, there are insufficient data to use K-RAS mutation status for lung cancer patient selection to EGFR inhibitor therapy." (PMID 21654681, 2011). "KRAS and EGFR mutation status has been analyzed in primary tumors in the majority of the current studies, but it has been demonstrated that lung cancers are often heterogeneous at the molecular level, even within the same tumor." (PMID 21414214, 2011). "In lung cancer, gain-of-function EGFR mutations have been shown to be predictive of sensitivity to EGFR-targeted treatments, however, in other tumor types, these mutations are either absent or are very rare." (PMID 21388543, 2011). "Of 198 patients with nonsmall cell lung cancer, we identified 52 (26.3%) patients with an EGFR mutation." (PMID 22191026, 2011). "The aim of this study is to optimize conditions for restriction enzyme-based mutant enriched detection of EGFR mutation in lung cancer specimens." (PMID 21859543, 2011). "Circumstantial support for this comes from studies showing high levels of Cten expression in lung cancer; tumours in this organ have a high frequency of disrupted EGFR/Kras signalling due to either Kras or EGFR mutation." (PMID 21698197, 2011).
lung cancer (continued). "Consistent with earlier reports, our results show that KRAS and BRAF mutation frequencies in colorectal cancer were 44.3% and 13.0%, respectively, while EGFR mutations were detected in 11.1% of the lung cancer specimens." (PMID 21943394, 2011). "We herein showed the frequency of EGFR mutation in nonsmall cell lung cancer to be high in patients with the following factors: female gender, no history of smoking, adenocarcinoma, and normal lungs on chest CT." (PMID 22191026, 2011). "Epidermal growth factor receptor (EGFR) gene mutation in lung cancer is a reliable predictor of the efficacy of tyrosine kinase inhibitors, so detection of gene mutation has very important clinical significance." (PMID 21859543, 2011). "Erlotinib performed best in lung cancers with high levels of EGFR activation and activating mutations in the kinase domain." (PMID 22091418, 2011). "The EGFR-activating mutations are present in a subset of central nervous system tumours and lung cancer, but are remarkably rare in breast cancer cell lines and human breast cancer samples." (PMID 21730982, 2011). "A recent report also suggested that the activating mutation of the EGFR gene occurs as an early event during carcinogenesis of lung cancer." (PMID 22108465, 2011). "It was later found that the subgroups of patients with nonsmall cell lung cancer who had sensitivity to gefitinib had a high incidence of EGFR mutations." (PMID 22191026, 2011). "As recorded in the Sanger Institute Catalogue of Somatic Mutations in Cancer data-base (COSMIC v49 Release), curated from the recent literature, a total of 22489 samples from lung cancer tumours have been analyzed for EGFR tyrosine kinase domain mutations." (PMID 21575252, 2011). "For example, treatment with small molecule inhibitors of the epidermal growth factor receptor (EGFR) has been shown to primarily benefit lung cancer patients that carry certain somatic mutations in their EGFR gene." (PMID 21701589, 2011). "This article summarizes the role of EGFR mutations in lung cancer and the use of EGFR antagonists in the treatment of lung cancer and its associated adverse effects." (PMID 24212826, 2011). "The frequency of EGFR mutations varies with the ethnicity, sex, smoking status, and histological type of lung cancer." (PMID 24212826, 2011). "The role of CYP1A1 polymorphism as a predictor of clinical outcome to EGFR-TKIs in patients with advanced lung cancer has very recently been reported." (PMID 22111840, 2011). "From these results, we can conclude that p.R776G, p.T790M, p.V843I and p.P848L are rare EGFR alleles that have been found in germ line from patients suffering lung cancer." (PMID 21575252, 2011). "The EGFR T790M/L858R double mutation is a common mutation that appears in clinical lung cancer patients treated with reversible inhibitors." (PMID 21789172, 2011). "The Spanish Lung Cancer Group trial observed a prevalence of EGFR mutations in patients with lung cancer in Spain around 16% (350 of 2,105 cases)." (PMID 21444946, 2011). "Previous reports in lung cancer patients have demonstrated that clinical benefit from tyrosine kinase inhibitors is greater in patients whose tumours harbour an EGFR mutation." (PMID 21811258, 2011). "Next, to further strengthen the role of BCRP/ABCG2 in influencing gefitinib sensitivity, the correlation between BCRP/ABCG2 expression and gefitinib sensitivity was evaluated in various lung cancer cell lines, which express either wild-type or mutated EGFR." (PMID 21731744, 2011). "Somatic KRAS mutations have been associated with resistance to EGFR-targeted agents in lung cancer and metastatic CRC, and are mutually exclusive with EGFR mutations in large series of NSCLC." (PMID 21943394, 2011). "Although 80% of lung cancer patients who are carriers of EGFR TK domain mutations experience partial responses or marked clinical improvement with gefitinib or erlotinib, patients without such mutations are refractory to these agents." (PMID 21730982, 2011).
lung cancer (continued). "Bim has also been shown to mediate epidermal growth factor receptor (EGFR) inhibitor–induced apoptosis in lung cancer cells that have EGFR or BRAF mutations." (PMID 20885957, 2010). "80% of colon cancers have APC mutations and 50-70% of breast, colon and lung cancers have EGFR and ErB3 mutations." (PMID 20828404, 2010). "In lung cancer, a series of mutations in the kinase domain was originally identified in correlation with sensitivity to EGFR inhibitors." (PMID 21165163, 2010). "Recently, small molecules have been developed to treat lung cancer in patients carrying such mutated genes as EGFR and EML4-ALK fusion genes." (PMID 21079797, 2010). "More recently, MET amplification and activation via HGF/SF has also been implicated in resistance to EGFR inhibition in lung cancer." (PMID 21049054, 2010). "Exemplifying this concept is the fact that chronic exposure to gefitinib, an agent that targets the EGFR, results in emergence of resistant lung cancer cells bearing a mutation in the EGFR that renders these tumoral cells insensitive to the drug." (PMID 20670437, 2010). "In lung cancer patients harboring these mutations, response rates to EGFR TKIs can be high and survival is better than that seen with cytotoxic agents." (PMID 20976048, 2010). "Epidermal growth factor receptor (EGFR) signalling and EGFR mutations have been a major focus of lung cancer studies conducted during the past 5 years." (PMID 20859290, 2010). "These authors also observed activation of a number of genes associated with lung cancer development, including EGFR (epidermal growth factor receptor), AFP (α-fetoprotein), and L‐myc (lung associated myc oncogene) after gestational exposure." (PMID 20444669, 2010). "Cellular mechanisms of resistance to EGFR small molecule inhibitors have best been studied in lung cancers containing EGFR sensitizing mutations." (PMID 20624308, 2010). "Certain molecular factors have been identified as predictive of EGFR TKI response in lung cancers, such as increased EGFR gene copy number and activating mutations within the EGFR TK domain." (PMID 21165163, 2010). "K-RAS mutations have been demonstrated to be significantly associated with primary resistance to EGFR-TKIs in a wide variety of tumor types including lung cancer." (PMID 21165163, 2010). "Previous studies from our lab and others have shown that East Asians with lung cancers have relatively high frequencies of gain-of-function of mutations in RTKs such as EGFR and MET." (PMID 20126411, 2010). "Leucine-to-arginine substitution at position 858 (L858R) and deletion mutants in exon 19 constitute 90% of lung cancer-specific EGFR-activating mutations." (PMID 20859290, 2010). "It has been demonstrated in lung cancer that EGFR and c-Met are linked via ERBB3 and this has been implicated in clinical resistance to EGFR TKIs." (PMID 21390244, 2010). "Scorpion ARMS can detect a lower proportion of mutant alleles than direct sequencing; we demonstrated that Scorpion ARMS was more sensitive than direct sequencing in detecting EGFR mutations in lung carcinomas in our previous study." (PMID 20637128, 2010). "In particular, EGFR is a receptor tyrosine kinase implicated in lung cancer and is involved in multiple biological processes, including apoptosis, cell adhesion, and growth." (PMID 19946374, 2009). "It has been found that there is a strong response of tyrosine kinase inhibitors (e.g. erlotinib and gefitinib) to lung cancers exhibiting EGFR activating-mutations." (PMID 21556249, 2009). "A spectrum of lung cancer-derived EGFR mutations can induce oncogenic transformation by leading to constitutive kinase activity and confer markedly different degrees of sensitivity to EGFR inhibitors." (PMID 19714203, 2009).
lung cancer (continued). "Earlier studies had identified a subset of lung cancer patients with rapid and durable clinical responses to EGFR TKIs and found an underlying association between activating mutations in the EGFR tyrosine kinase domain and therapy response." (PMID 19174819, 2009). "Pathways downstream of the EGFR and Met receptors, with prominent roles in lung cancer biology, were similarly implicated." (PMID 19946374, 2009). "In lung cancer, shorter EGFR intron 1 CA repeat polymorphism has been reported to be associated with improved response to gefitinib in two independent studies." (PMID 19636423, 2009). "EGFR overexpression and its activating-mutations at exons 18–21 in lung cancers have been extensively studied." (PMID 21556249, 2009). "Gefitinib was reported to be effective not only in lung cancers with EGFR mutations, but also for lung or colorectal cancers expressing EGFR protein or with increased EGFR gene copy number." (PMID 18950515, 2008). "Retrospective and prospective data in lung cancer indicate that an EGFR mutation is a stronger predictor for response and outcome under treatment with tyrosine kinase inhibitors than increased copy number." (PMID 18182111, 2008). "Others have performed mutation analysis limited to the exons of the tyrosine kinase domain of EGFR known be mutated in lung cancer." (PMID 18182111, 2008). "Dramatic responses observed in lung cancer correlate strongly with the presence of EGFR tyrosine kinase domain mutations." (PMID 18182111, 2008). "Four triplets and one quadruplet in EGFR were found at a frequency of 0.3% (5/1627) of lung cancers with mutations prior to treatment with tyrosine kinase inhibitor (TKI)." (PMID 19005564, 2008). "In lung cancer, the two most common types of EGFR mutation, exon 19 deletions and exon 21 p.L858R, were screened by HRM, with a reported 92% sensitivity compared with direct sequencing." (PMID 18495026, 2008). "A recent paper showed that the p14/ARF protein was frequently down regulated in lung cancers with EGFR mutation or in tumors with ERBB2 mutations." (PMID 18549475, 2008). "In many studies in lung cancer, but also in other cancers, EGFR mutation analysis has been restricted to the exons known to be frequently mutated." (PMID 18182111, 2008). "In contrast, most previous studies on EGFR gene mutations or copy number analyses in lung cancer were based on resection specimens or biopsy material." (PMID 18087280, 2008). "The Spanish Lung Cancer Group also reported on a prospective phase II study of erlotinib in advanced NSCLC patients with EGFR mutations." (PMID 18283321, 2008). "In lung cancer studies the majority of cancer associated somatic mutations occur in the tyrosine kinase domain of EGFR and Her-2 neu mainly in exon 18–21 and exon 19–20 respectively." (PMID 18182111, 2008). "In order to improve our knowledge of lung cancer biology in non-smokers, one of the first questions to answer is: what are the molecular alterations associated to EGFR mutations in lung cancer?" (PMID 18549475, 2008). "This is the first report of the detection of an EGFR hot-spot mutation (known from lung cancer to be correlated to gefitinib/erlotinib therapy sensitivity) in SGCs." (PMID 18542074, 2008). "When EGFR mutations were first reported, the most exciting finding was that lung cancer harbouring this genetic alteration showed a striking response to EGFR-TKIs." (PMID 17325698, 2007). "Characterisation of lung cancers with TKI-sensitive EGFR mutations reveals that PI3K/Akt pathway in these tumours is dependent on HER3 signalling." (PMID 17667926, 2007). "The models should also be useful for developing improved therapies for patients with lung cancers harboring EGFRT790M alone or in conjunction with drug-sensitive EGFR kinase domain mutations." (PMID 17726540, 2007).